RECQL4 (RecQ like helicase 4)
Diseases named in the same sentence as RECQL4 in open-access papers (continued):
Sharing a sentence is not in itself a finding about the gene and the disease.
cancer (continued). "Accumulating evidence indicates that RECQL4 functions as an oncogene and facilitates the advancement of multiple cancer types." (PMID 41513625, 2026). "In fact, reducing the expression level of RECQL4 to that of normal cells is sufficient enough to abolish the tumorigenic potential of cancer cells." (PMID 41513625, 2026). "Given the demonstrated roles of RECQL4 in maintaining genomic stability and facilitating cancer progression, targeting RECQL4 appears to be a promising strategy for cancer treatment." (PMID 41513625, 2026). "Considering the rapid proliferation of cancer cells, the development of novel tumor-specific targeting strategies aimed at DNA replication and repair factors, such as RECQL4, holds great promise for cancer treatment." (PMID 41513625, 2026). "In conclusion, we provide compelling new evidence for a reversible covalent inhibitor that targets RECQL4 helicase activity in endresection and potentially will benefit patients in cancer treatment." (PMID 40196015, 2025). "The prognostic significance of RECQL4 alterations, coupled with its potential role as a predictive biomarker for immunotherapy response, underscores the clinical relevance of targeting RECQL4 in cancer therapy." (PMID 39812592, 2025). "In conclusion, our comprehensive analysis sheds light on the complex interplay between RECQL4 amplification, genomic instability, immune modulation and clinical outcomes in cancer." (PMID 39812592, 2025). "Defining the molecular consequences of different RECQL4 mutations is imperative to expand our understanding of clinical phenotypes, and the dual roles of RECQ4 in cancer development and suppression." (PMID 41419455, 2025). "When analysing tissue characteristics of the MSK‐MET cohort, we identified a significantly increased level of tumour purity in tumours harbouring RECQL4 high amplifications (p < .05), implicating a larger fraction of cancer cells in the tumour mass." (PMID 39812592, 2025). "To assess if high mRNA RECQL4 expression relates to cancer genomic instability, we utilized pan-cancer data from the cBioPortal that examined copy number alterations and mutations." (PMID 40196015, 2025). "Increasing evidence suggests that RECQL4 protects cancer cells from endogenous and exogenous DNA damage." (PMID 39870799, 2025). "The potential association between RECQL4 high amplification and the host immune response in cancer patients captured our interest, prompting us to compares intra‐tumoural immune cell infiltration across various RECQL4 CNA within the TCGA SKCM cohort." (PMID 39812592, 2025). "Continuous upregulation of RECQL4 in highly proliferative conditions, such as cancer development, argues for its suitability as a therapeutic target." (PMID 39812592, 2025). "Germline defects in RECQL4 and other genes from the family: RECQL1, BLM, WRN results in syndromes associated with premature aging and predisposition to cancer." (PMID 41419455, 2025). "We found that a small number of genes (e.g., RET, RECQL4, CUX1, FGFR4, PIK3R1, FGFR3, and GNAS) had some co-occurring variants per patient in different cancer types." (PMID 38637555, 2024). "Initially, the co-expression of RECQs on the genome level was investigated in pan-cancer, revealing a robust association between BLM and RECQL4." (PMID 37626815, 2023). "Some of the genes encompassed by these CNAs are known cancer genes and have been previously associated with OS pathogenesis, such as MYC, RB1, and RECQL4." (PMID 37445641, 2023). "This work focuses on the central role of RECQL4 in promoting and suppressing tumors in different types of cancer." (PMID 37626815, 2023). "Future therapies can potentially use compounds like heliquinomycin to inhibit RECQL4-induced replication of cancer cells." (PMID 35782872, 2022).
cancer (continued). "In our cohort, fourteen patients harbored a monoallelic P/LPV associated with recessive disorders (NTHL1, RECQL4, ERCC3, FANCA, and BLM) and one patient harbored PV in a low penetrance cancer gene (TYR)." (PMID 36132150, 2022). "Strikingly, increased expression of RecQ helicases and RecQL4 in particular is observed in many human cancer types." (PMID 35935726, 2022). "We found positive LASSO coefficients for the genes CDKN2A, EGLN3, KIF14, and RECQL4 that were upregulated in cancer compared with normal samples." (PMID 36552262, 2022). "Our result is consistent with another study where RECQL4 expression was elevated in more aggressive cancers." (PMID 36126066, 2022). "In recent years, abnormal high RECQL4 expression has been reported in numerous cancers by a body of studies." (PMID 34486474, 2021). "Intriguingly, RECQL4 is located on chromosome 8q24, which is a particular hotspot for overexpression in cancer as it is near the oncogene, c-Myc." (PMID 34946868, 2021). "In a study of cancer cells containing an inactivated RECQL4 gene and upregulated RAD52, inhibition of RAD52 sensitized the cancer cells to ionizing radiation." (PMID 34887904, 2021). "This suggests that the helicase function of RECQL4 is critical for maintenance of genomic stability and subsequent cancer prevention." (PMID 34946868, 2021). "Kitao and coworkers investigated RECQL4 because RTS patients have chromosomal instability, growth retardation, hypogonadism and cancer predisposition similar to individuals with Bloom or Werner syndrome." (PMID 33477564, 2021). "While RECQL4 is critical for genome maintenance and subsequent disease/cancer prevention, overexpression of RECQL4 is observed in a variety of different cancers." (PMID 34946868, 2021). "The average size and weight of tumors formed by RECQL4 knockdown cancer cells at the final experimental endpoint was significantly reduced." (PMID 33628589, 2021). "We found that somatic genomic alterations of the RECQL4, JAK3, ARID1A, and MAGI1 genes, combined with MBs, were associated with the development of metachronous cancers after curative ESD and successful HP eradiation." (PMID 33328548, 2020). "Biallelic mutations in RECQL4 gene, a caretaker of the genome, cause Rothmund-Thomson type-II syndrome (RTS-II) and confer increased cancer risk if they damage the helicase domain." (PMID 29642415, 2018). "These interesting aspects have to be investigated further to verify the multifaceted roles of RecQL4 in cancer cells." (PMID 30206236, 2018). "Given the high incidence of OS in RTS patients, we established cohorts of Osx-Cre Recql4+/+, Osx-Cre Recql4fl/+ and Osx-Cre Recql4fl/fl mice that were allowed to age and were monitored for the development of cancer, particularly OS." (PMID 25859855, 2015). "Along with RECQL4, WRN and BLM are also associated with human hereditary disorders involving both skeletal defects and cancer predisposition." (PMID 25859855, 2015). "Expression of RecQL4 was next monitored at the protein level by western blot using the whole cell lysates of normal breast epithelial cells and cancer cell lines." (PMID 23894508, 2013). "Mutations in three of these helicase genes, RECQ2 (BLM), RECQ3 (WRN) and RECQL4, result in the rare autosomal recessive disorders of Bloom, Werner and RTS, which share the general characteristics of genomic instability and cancer predisposition." (PMID 20113479, 2010). "Since most cells in the body, with the exception of adult stem cells, are primarily in a quiescent state, targeting the DNA replication machinery through RECQL4 may hold great promise for cancer treatment." (PMID 41513625, 2026). "So far, we have demonstrated the pan‐cancer role of RECQL4 CNA." (PMID 39812592, 2025).
cancer (continued). "Given the demonstrated roles of RECQL4 in cancer, it is logical to assume that therapeutic targeting may be an effective strategy for cancer therapy." (PMID 39812592, 2025). "A deeper understanding of the molecular mechanisms by which RECQL4 regulates the immune system may facilitate the development of innovative therapeutic strategies to enhance the clinical efficacy of immunotherapy in cancer patients." (PMID 39812592, 2025). "RECQL4 is highly overexpressed in many cancers but it is unknown whether RECQL4 acts as a tumor suppressor or an oncogene." (PMID 41419455, 2025). "Overall, a germline pathogenic variant (gPV) in a cancer predisposing gene was identified in 9.7% of individuals (CHEK2, FANCM, NF1, POT1 and PTEN) and a candidate variant in 4.2% of individuals (HOXB13, MAX and RECQL4)." (PMID 39979679, 2025). "In addition, more insights in RECQL4‐driven signalling pathways in large patient cohorts under ICI therapy are needed to better understand the impact of REQCL4 on cancer‐related modulators that influence disease progression and ICI response." (PMID 39812592, 2025). "Patients with biallelic gPVs in RECQL4 have been found to develop cancer and other genes that are a part of the RECQL gene family, including RECQL2 (OMIM: 604611) and RECQL3 (OMIM: 604610) have been associated with syndromes predisposing to both malignant and benign neoplasms." (PMID 39979679, 2025). "Our findings unraveled the pivotal role of RECQL4 in immune modulation and its potential as both a predictive biomarker and therapeutic target for optimising immunotherapeutic strategies across various cancer types." (PMID 39812592, 2025). "UBE2M, FN1, and RECQL4, for example, fell among our top 12 common-cancer seed hubs." (PMID 39657701, 2024). "Human cells lacking mitochondrial RECQL4 exhibit increased reactive oxygen species, mtDNA mutations, and altered metabolism phenotype that leads to cancer predisposition." (PMID 37495109, 2023). "Moreover, it was found that RECQs exhibited a notable variation in prognosis across different types of cancers, with RECQL, BLM, and RECQL4 showing promising diagnostic potential in LIHC." (PMID 37626815, 2023). "Overall, our study identifies a conserved role for RECQL4 in DNA intrastrand crosslink repair and provides insights into how its misregulation could promote cancer development." (PMID 36126066, 2022). "In each cancer type, high levels of RECQL4 are correlated with poor prognosis." (PMID 36126066, 2022). "Two CNVs (chromosome 8q24.22-q24.3 and 11p11.2-p12 deletion) encompassed known germline cancer-predisposing genes (RECQL4 and EXT2, respectively) and were not appeared in the DGV database, indicating both CNVs were probably damaging." (PMID 35860547, 2022). "In addition, 2 of 70 patients with IPMN (2.8%) had cancer-related variations, and both were splice-site variations (RECQL4 c.2755 + 1G>A and ATM c.3576 + 1G>A)." (PMID 35171259, 2022). "Other mutated cancer genes included those involved in Wnt signaling (APC, AMER1), mitogen signaling (KRAS, BRAF), epigenetic modification (ARID1A, ARID2, DNMT3A, NCOA3) and DNA repair (RAD50, BRIP1, ERCC5, RECQL4)." (PMID 33776923, 2021). "Since RECQL4 is often overexpressed in cancer cells, it would be critically important to determine whether RECQL4 has a stimulatory or inhibitory effect on telomerase in cancer." (PMID 34946868, 2021). "Besides its role in modulating proteins critical for cellular survival and drug resistance, RECQL4 can also support cancer progression and survival by its replicative and DNA repair roles." (PMID 34946868, 2021). "Moreover, depletion of RECQL4 in cancer cells has been shown to significantly reduce cell proliferation and cell invasion potential, promote apoptosis, and impair tumorgenicity in tumor-bearing mice." (PMID 33628589, 2021).
cancer (continued). "In this study, somatic alterations of two cancer-related genes, including the RECQL4 and the JAK3, had significant associations with non-MGC development, and the ARID1A and the MAGI1 genes had significant associations with metachronous development." (PMID 33328548, 2020). "RECQL4 has been found to be highly amplified in many cancers." (PMID 33014878, 2020). "The high frequency of chromosome abnormalities found in cells from RTS patients and the increased cancer incidence rates, suggest that RECQL4 may have a role in maintaining genome stability through DNA repair." (PMID 31276497, 2019). "Interestingly, expression of RECQL4 in three cancer cell lines (HeLa, HEK293, and U2OS) significantly exceeds that in fibroblasts." (PMID 30718377, 2019). "RecQ-like helicase 4 (RECQL4) is mutated in patients suffering from the Rothmund–Thomson syndrome, a genetic disease characterized by premature aging, skeletal malformations, and high cancer susceptibility." (PMID 30718377, 2019). "It is likely that hTERT activation leads to RecQL4 upregulation, which in turn can protect the telomere stability in cancer cells both by its unwinding and DNA repair activities, and meanwhile, both RecQL4 and AURKB work in a concerted manner to achieve the telomeric stability in cancer cells." (PMID 30206236, 2018). "It is tempting to speculate that the elevated expression of RecQL4 confers survival advantage to cancer cells by protecting them from mitotic irregularities through upregulation of AURKB." (PMID 30206236, 2018). "Elevated expression of the DNA helicase genes BLM, PIF1, and RECQL4 which is generally observed in cancers may explain a recovery function from chromatin instability in ST2." (PMID 25460179, 2014). "Association of RecQL4 elevated expression with prostate and breast carcinogenesis indicates the possibility that RecQL4 may be a major replicative helicase for cancer cells." (PMID 23894508, 2013). "Thus, both amplification of RecQL4 genomic locus and the transcriptional mechanism(s) probably contribute to the up-regulation of RecQL4 expression in human cancer cells." (PMID 23894508, 2013). "Therefore, any strategy that targets RECQL4 must be highly specific to cancer cells." (PMID 41513625, 2026). "In addition, we performed survival analyses in these cancer cohorts to investigate whether RECQL4 high amplification correlated with patient's prognosis." (PMID 39812592, 2025). "Hence, targeting of RECQL4 may constitute an effective strategy to prevent cancer recurrence through depletion of cancer stem cells." (PMID 39812592, 2025). "Therefore, combination therapy with RECQL4 or PolQ inhibition could be a potential cancer therapy approach." (PMID 39870799, 2025). "Notably, patient 21 had no family history of cancer but was found to harbor a pathogenic mutation in RECQL4, which has been implicated in type II Rothmund–Thomson syndrome characterized by a premature aging phenotype." (PMID 38661052, 2024). "Since RECQL4 is an important hallmark molecule for stratifying HCC patients, it may be involved in T cell‐mediated cancer cell sensing and killing, we propose that RECQL4 might serve as a potential target for DNA damage repair in HCC in a designated subpopulation of HCC patients." (PMID 38381090, 2024). "Consequently, RTS patient cells lacking RECQL4 have mutations incorporated in their mtDNA that are associated with aging and/or cancer." (PMID 37495109, 2023). "All RECQL4-negative RTS patients are not at an increased risk of cancer." (PMID 20113479, 2010). "The top 200 linear model genes were screened against the known cancer driver genes in Cancer Gene Census, yielding four hits: BUB1B, EBF1, PPARG, and RECQL4." (PMID 41048341, 2025). "While UBE2M, is only recently starting to be envisaged as a cancer player, FN1 and RECQL4 are two well-known oncogenes." (PMID 39657701, 2024).
cancer (continued). "In our research, we also discovered consistent findings, and RECQL4 exhibited a robust correlation with TMB and MSI in numerous types of cancer." (PMID 37626815, 2023). "Conversely, BLM, RECQL4, and RECQL5 displayed diverse correlations with stem cell scores across different types of cancers." (PMID 37626815, 2023). "BLM, WRN, RECQL4, and RECQL5 were repressed by stromal and/or immune elements in most types of cancer, while RECQL exhibited reverse patterns." (PMID 37626815, 2023). "Thus, targeting RECQL4 helicase may be an avenue for novel cancer treatment." (PMID 35267530, 2022). "Several of them were involved synthetically lethal genetic interactions, especially for RECQL4, TOP2A, MKI67 and ASPM, indicating their potential roles in drug design and cancer treatment." (PMID 32040444, 2020). "Amplification-dependent overexpression of RecQ protein-like 4 (RECQL4), which participates in DNA replication and repair, mediates the development of various cancers, but its pathobiological and clinical roles are poorly understood." (PMID 33014878, 2020). "On screening the top 200 linear model genes against cancer driver genes in the Cancer Gene Census, only four genes were found, namely BUB1B, CDKN2A, EZH2, and RECQL4." (PMID 31277598, 2019). "In corroboration with aberrant elevation of RecQL4 in human cancers, abnormal activation of AURKB was also observed to be a frequent event in human cancer cells." (PMID 30206236, 2018). "The other five genes: RECQL4, MYCL1, KDM5C, NUMA1, and PCM1 are documented in the cancer Gene Census list." (PMID 26998479, 2015). "These deletions contained known cancer genes based on the Sanger Census cancer gene list, including FGFR3, RECQL4, NOTCH1, PTEN, TSC2, and/or ASPSCR1 which suggested their roles as tumor suppressor genes in the development of HCC." (PMID 25469175, 2014). "The evidence presented here denotes RECQL4 as an important nitroalkene target conferring DSB repair inhibition and supports further evaluation of nitroalkenes as therapeutic agents in RECQL4-amplified cancers." (PMID 40196015, 2025). "The RECQL4 helicase is responsible for preventing multiple clinical syndromes, cancer and premature aging but its role has not been clarified." (PMID 41419455, 2025). "Yet, the precise role of RECQL4 in cancer progression requires further elucidation and overarching cancer studies are lacking." (PMID 39812592, 2025). "Taken together, the results showed that the expression of RECQL4 was upregulated during the clinical progression of ESCC, indicating that the expression of RECQL4 may have induced the progression of ESCC cancer." (PMID 33628589, 2021). "Although she had an extensive personal history of cancer suggestive of cancer predisposition, her clinical phenotype and family history would not have predicted either BAP1 or RECQL4 mutations prior to testing." (PMID 33541411, 2021). "RECQL4 interacts and may cooperate in DNA repair with Poly(ADP-ribose) polymerase (PARP), and PARP inhibitors show synthetic lethality in diverse cancer cells with defective DNA repair." (PMID 33050631, 2020). "Distinct RECQL4 mutations are also linked to the RAPADILINO syndrome, indicated by skeletal malformations but no cancer predisposition, and the Baller–Gerold syndrome, characterized by bone abnormalities of the skull, arms, and hands." (PMID 30718377, 2019). "Consequently, it is not necessary to entirely eliminate RECQL4 to achieve the destruction of cancer cells, which allows for the preservation of healthy normal cells." (PMID 41513625, 2026). "Functional autosomal recessive loss of three members of the family BLM, WRN and RECQL4, results in hereditary human syndromes characterized by cancer predisposition and premature aging, but despite the finding that RECQL5 deficient mice are cancer prone, no such link has been made to human RECQL5." (PMID 27764811, 2016).